BCL7A (BAF chromatin remodeling complex subunit BCL7A)
Synonyms: SMARCJ1; BCL7
Tractability: PROTAC: UniProt records ubiquitination sites on it; ubiquitination databases record sites on it; its protein half-life has been measured.
Gene: Protein-coding gene on chromosome 12 (122,019,422 to 122,062,044, forward strand). Ensembl gene ENSG00000110987.
Subcellular location (Human Protein Atlas): Nucleoplasm; Vesicles
Pathways (Reactome):
Chromatin organization: Formation of neuronal progenitor and neuronal BAF (npBAF and nBAF); Formation of the canonical BAF (cBAF) complex; Formation of the embryonic stem cell BAF (esBAF) complex; Formation of the non-canonical BAF (ncBAF) complex; Formation of the polybromo-BAF (pBAF) complex
Developmental Biology: Regulation of MITF-M-dependent genes involved in pigmentation
Gene expression (Transcription): Regulation of endogenous retroelements by Piwi-interacting RNAs (piRNAs)
Gene Ontology:
Molecular function: protein binding
Biological process: chromatin remodeling; negative regulation of cell differentiation; negative regulation of DNA-templated transcription; positive regulation of cell population proliferation; positive regulation of double-strand break repair; positive regulation of stem cell population maintenance; regulation of G0 to G1 transition; regulation of G1/S transition of mitotic cell cycle; regulation of mitotic metaphase/anaphase transition; regulation of nucleotide-excision repair; regulation of transcription by RNA polymerase II
Cellular component: SWI/SNF complex; chromatin; GBAF complex; nucleoplasm
Genetic constraint (gnomAD): Loss-of-function variants: 11 observed, 26.58 expected, observed/expected ratio (o/e) 0.41, 90% interval 0.26 to 0.69. The upper end of that interval is the gene's LOEUF score, 0.69, which puts it in group 2 of 6, group 1 being the genes least tolerant of losing a copy. Missense variants: 221 observed, 268.13 expected, observed/expected ratio (o/e) 0.82, 90% interval 0.74 to 0.92. Synonymous variants: 123 observed, 102.91 expected, observed/expected ratio (o/e) 1.2, 90% interval 1.03 to 1.39.
Homologues: Orthologues: chimpanzee BCL7A (100% identical), macaque BCL7A (99% identical), dog BCL7A (95% identical), pig BCL7A (95% identical), mouse Bcl7a (94% identical), rabbit BCL7A (93% identical), rat Bcl7a (73% identical), guinea pig BCL7A (72% identical), tropical clawed frog bcl7a (67% identical), zebrafish bcl7a (64% identical), Drosophila melanogaster BCL7-like (31% identical), Caenorhabditis elegans bcl-7 (23% identical). Paralogues in human: BCL7B (45% identical), BCL7C (36% identical).
Diseases named in the same sentence as BCL7A in open-access papers:
BCL7A is named in the same sentence as 44 diseases in open-access papers, as found by Europe PMC text mining. Sharing a sentence is not in itself a finding about the gene and the disease. The quoted sentences say what the papers report.
Burkitt lymphoma (6 papers, 2019 to 2023). A rare form of malignant mature B-cell non-Hodgkin lymphoma. "BCL7A is the most well-studied BCL7 protein because of its role in the pathogenesis of Burkitt’s lymphoma as part of a three-gene translocation event." (PMID 36801810, 2023). "The BCL7 family was first discovered when B-cell CLL/lymphoma 7 protein family member A (BCL7A) was found to be involved in the complex translocation of a Burkitt lymphoma cell line." (PMID 35910232, 2022). "Previous studies have proved that increased BCL7A protects from Burkitt lymphoma, astrocytoma, cutaneous T-cell lymphoma, B-cell non-Hodgkin’s lymphoma, and osteosarcoma." (PMID 35910232, 2022). "Whilst acknowledging the wide studies of BCL7A in multiple lymphoid neoplasms, including Hodgkin lymphoma, T cell lymphoma, and Burkitt lymphoma, it was less explored in solid tumors." (PMID 34362400, 2021). "In contrast to SMARCA2/4 and ARID1A/1B/2 genes, BCL7A seems to be specifically mutated in lymphomas that are either derived from or phenotypically similar to germinal center B cells, such as germinal center B cell-like (GCB) DLBCL, FL, Burkitt lymphoma (BL), and MM." (PMID 36810086, 2023). "The first group included patients [three patients with diffuse large B-cell lymphoma (DLBCL) and one patient with Burkitt lymphoma] who exhibited gain of chromosome 12, which is where STAT6, MDM2, and BCL7A are located." (PMID 34710202, 2021). "BCL7A was originally cloned from the chromosome translocation of the Burkitt lymphoma cell line and it can interact with SWI/SNF components, suggesting that BCL7A participates in the progression of cancer cells by chromatin remodelling." (PMID 31077237, 2019).
diffuse large B-cell lymphoma (6 papers, 2019 to 2026). "Deletion of 27 amino acids occurs in the N-terminal domain of BCL7A in diffuse large B-cell lymphomas (DLBCL) due to a recurrent mutational hotspot at the splice donor site of intron 1, which prevents the SWI/SNF complex assembly." (PMID 39471843, 2024). "The subunit BCL7A often undergoes functional inactivation in Diffuse Large B cell lymphoma (DLBCL) because of bi-allelic mutations that damage its tumor suppression abilities." (PMID 36941700, 2023). "Recent studies have found that BCL7A expression is increased in diffuse large B-cell lymphoma (DLL) but decreased in mycosis fungoides (MF) and peripheral T-cell lymphoma (PTCL)." (PMID 31077237, 2019). "BCL7A, a tissue-specific, non-catalytic subunit of this complex, exhibits tumor--suppressive activity, especially in diffuse large B-cell lymphoma (DLBCL)." (PMID 41485079, 2026).
lymphoma (5 papers, 2007 to 2023). A malignant (clonal) proliferation of B- lymphocytes or T- lymphocytes which involves the lymph nodes, bone marrow and/or extranodal sites. "Here, we study the SWI/SNF subunit BCL7A, which has been found to be recurrently mutated in lymphomas, but whose role in acute myeloid malignancies is currently unknown." (PMID 36941700, 2023). "BCL7A, IGLL5, and BCL2 are likely false positives as they were mutated primarily in lymphomas, where they are known targets of local AID-mediated somatic hypermutation." (PMID 36396655, 2022). "BCL7A protein was mainly expressed in precursor and mature B cell lymphomas, especially in germinal center (GC)-related lymphomas." (PMID 34362400, 2021). "Also, the involvement of BCL7A locus in a recurrent breakpoint in lymphomas and MYC-BCL7A fusion transcript in Wien 133 cells had earlier been demonstrated." (PMID 34362400, 2021). "In addition, BCL7A and TNFA were previously reported as the prognostic factors for lymphoma." (PMID 17888167, 2007).
B-cell lymphoma (4 papers, 2017 to 2021). "BCL7A has been shown to be directly involved in a three-way gene translocation with Myc and IgH in high-grade B-cell non-Hodgkin lymphoma cell lines." (PMID 29166413, 2017).
glioma (4 papers, 2021 to 2024). A benign or malignant brain and spinal cord tumor that arises from glial cells (astrocytes, oligodendrocytes, ependymal cells). "Cox regression analysis identified BCL7A as the only gene in the BCL7 family that was independently associated with the prognosis of lower-grade glioma (LGG) and glioblastoma (GBM)." (PMID 34362400, 2021). "The survival analysis further suggested the regulatory correlation: elevated FAM18A-AS1 and miR-21 were associated with poor prognosis in glioma, and low expression of BCL7A, SATB1, and CPEB3 was associated with favorable prognosis." (PMID 35069683, 2021). "BCL7A was the only gene among the BCL7 family that independently was associated with the prognosis of glioma patients." (PMID 34362400, 2021). "The present study implicates BCL7A as a new tumor suppressor gene, negatively associated with glioma malignancy." (PMID 34362400, 2021). "For example, the significant increase in BCL7A during the pathological process of glioma can significantly reduce patients’ overall survival time, and has diagnostic value for the prognosis of patients." (PMID 38552216, 2024). "The level of BCL7A expression was significantly lower in glioma tissues compared to healthy brain tissue, and its expression was negatively correlated with glioma grade." (PMID 36425564, 2022). "BCL7A is a new tumor suppressor gene and can be adopted as a biomarker for independent prognosis in glioma and to evaluate response to TMZ." (PMID 34362400, 2021). "Results of survival analysis demonstrated that glioma patients with high BCL7A expression presented a higher percentage of OS than patients with low BCL7A expression in CGGA and TCGA (HR = 0.475 and 0.185, respectively, all p < 0.05)." (PMID 34362400, 2021). "Further, it was argued that BCL7A potentially plays a crucial role in the malignancy process of glioma." (PMID 34362400, 2021). "IHC analysis revealed robust infiltration of neutrophil in the glioma tissues of low BCL7A expression; however, less infiltration of neutrophil occurred in tissues of high BCL7A expression." (PMID 34362400, 2021). "BCL7A mRNA expression was significantly low in glioma tissues compared to normal brain tissues (NBTs) in 7 out of the 8 datasets, except for the Gravendeel dataset." (PMID 34362400, 2021). "Results demonstrated that GBM expressed significantly lower levels of BCL7A mRNA compared to lower-grade glioma (WHO I–III)." (PMID 34362400, 2021). "Herein, we demonstrated the BCL7A expression pattern in glioma for the first time." (PMID 34362400, 2021). "Notably, BCL7A expression was negatively associated with MGMT expression in four public datasets; its expression was highly enriched in MGMT methylated glioma." (PMID 34362400, 2021). "We also investigated the prognostic role of BCL7A for the first time in glioma." (PMID 34362400, 2021). "Since BCL7A expression is highly enriched in mesenchymal GBM and strongly associated with immune response in glioma, we attempted to explore whether BCL7A functioned as a predictive biomarker for positive adjuvant chemotherapy response." (PMID 34362400, 2021). "Results showed that high WHO grade (IV), IDH 1/2 wildtype, and low BCL7A expression could be used independently to predict the prognosis of all-gliomas patients based on TCGA and CGGA datasets (respectively)." (PMID 34362400, 2021). "However, BCL7A expression decreased progressively with higher glioma grade in two public datasets." (PMID 34362400, 2021). "Besides, the mechanism by which BCL7A influences glioma cells in vitro remains unclear, which should be established through molecular biology experiments." (PMID 34362400, 2021). "However, subsequent studies should mainly focus to elucidate the role of BCL7A in glioma." (PMID 34362400, 2021). "Furthermore, BCL7A expression was negatively correlated with glioma grades." (PMID 34362400, 2021).
glioma (continued). "Low expression of BCL7A in IDH wildtype and mesenchymal glioma tissues indicates that it potentially mediates the IDH-induced EMT." (PMID 34362400, 2021). "We found low BCL7A expression in 12 of 16 studies and high BCL7C expression in 11 of 12 studies in brain and CNS cancer." (PMID 34362400, 2021). "Thus, the present study strongly implicates BCL7A as a novel tumor suppressor gene, pivotal for predicting the response to TMZ in glioma." (PMID 34362400, 2021). "Significantly lower BCL7A expression was found in glioma tissues compared to non-tumor brain tissues." (PMID 34362400, 2021). "BCL7A expression in glioma tissues was lower compared to non-tumor brain tissues (NBT), and exhibited a negative correlation with glioma grades." (PMID 34362400, 2021). "Notably, the expression of BCL7A and BCL7C was significantly lower and higher in glioma tissues, respectively, compared to non-tumor brain tissues (NBT)." (PMID 34362400, 2021).
cutaneous melanoma (3 papers, 2021 to 2022). A primary melanoma arising from atypical melanocytes in the skin. "After correcting for multiple testing, the only significant promoters were TERT in cutaneous melanoma and pan-cancer; BCL7A, IGLL5, BCL2, and POLR3E pan-cancer; and HNRNPR in uterine adenocarcinoma." (PMID 36396655, 2022).
gastric cancer (3 papers, 2015 to 2021). A primary or metastatic malignant neoplasm involving the stomach. "A previous study, in a gastric cancer cell line, showed that quercetin and isoliquiritigenin decreased DNMT1 and DNMT3a protein levels, causing slight demethylation of the promoter region of the BCL7A gene." (PMID 30409182, 2018).
cutaneous T cell lymphoma (2 papers, 2019 to 2021). "Previous studies have found that early-stage cutaneous T-cell lymphoma patients with low expression of BCL7A were more likely to have a poor prognosis." (PMID 31077237, 2019). "In addition, BCL7A was found to be highly methylated in patients with cutaneous T-cell lymphoma and was identified as a marker of a poor prognosis in early-stage cutaneous T-cell lymphoma patients." (PMID 31077237, 2019). "By screening differential methylation between 28 patients with primary cutaneous T-cell lymphoma (CTCL) and benign T-cell samples, BCL7A demonstrated a higher frequency of hypermethylated." (PMID 34362400, 2021).
ovarian carcinoma (2 papers, 2019 to 2021). A malignant neoplasm originating from the surface ovarian epithelium. "A multivariate Cox model suggested that low BCL7A expression was an independent risk factor for ovarian cancer patients’ relapse-free survival (HR = 3.65, P = 0.011)." (PMID 31077237, 2019). "A multivariate Cox model suggested that low BCL7A expression was an independent risk factor for ovarian cancer patients’ overall survival (HR = 1.52, P = 0.005)." (PMID 31077237, 2019). "A Cox regression model showed that low expression of BCL7A was an independent risk factor for a poor outcome of ovarian cancer patients." (PMID 31077237, 2019). "Low BCL7A expression is an independent risk factor for poor prognosis in ovarian cancer patients." (PMID 31077237, 2019). "However, the association between BCL7A and overall survival was previously unknown in ovarian cancer." (PMID 31077237, 2019). "Elsewhere, ovarian cancer (OC) patients with high expression of BCL7A had shorter overall survival (OS) /progression-free survival (PFS) than those with low levels of BCL7A." (PMID 34362400, 2021). "Survival analysis showed that, compared with those who had higher levels of BCL7A expression, patients with ovarian cancer and low levels of BCL7A generally had shorter overall/relapse-free survival times." (PMID 31077237, 2019). "Survival analysis and a Cox regression model were employed to identify the correlation between BCL7A and ovarian cancer patients’ survival rate." (PMID 31077237, 2019). "As a result, we found that BCL7A is expressed at low levels in ovarian cancer tissues and is correlated with survival status." (PMID 31077237, 2019). "In this work, we found that the overall survival time was significantly shorter when ovarian cancer patients had low BCL7A expression." (PMID 31077237, 2019). "In this study, we found that the overall survival time of ovarian cancer patients was shorter when BCL7A was expressed at low levels." (PMID 31077237, 2019). "To further evaluate the clinical significance of BCL7A in the prognosis of ovarian cancer patients, we examined the differential expression of BCL7A mRNA in ovarian cancer by exploring the Cancer Genome Atlas database (TCGA)." (PMID 31077237, 2019). "Boxplots revealed that lower BCL7A expression was found in ovarian cancer tissues compared with normal ovarian tissues." (PMID 31077237, 2019). "Cox regression models showed that low BCL7A expression could be used as an independent prognostication factor for ovarian cancer patients." (PMID 31077237, 2019). "In conclusion, we generally focused on the prognostic value of BCL7A for ovarian cancer patients." (PMID 31077237, 2019). "We aimed to study the prognostic role of BCL7A in ovarian cancer." (PMID 31077237, 2019). "Therefore, it is necessary to understand the role of BCL7A in ovarian cancer further." (PMID 31077237, 2019). "However, the role of BCL7A in ovarian cancer remains unclear." (PMID 31077237, 2019). "Unlike these studies, we have found that BCL7A expression was downregulated in ovarian cancer tissues compared with normal ovarian tissues, which might be due to the different expression and functions of BCL7A in different tissues." (PMID 31077237, 2019).
T -cell lymphoma (2 papers, 2011 to 2021). "The specific function of BCL7A has not yet been determined, however, it may play a role in T -cell lymphoma." (PMID 22003408, 2011).
Allergy (1 paper, 2021). An allergy is an immune response or reaction to substances that are usually not harmful. "Comparing the direction of methylation to the independent allergy data set, four genes exhibited the opposite direction of patterning (HIVEP3, TRAT1, BCL7A and SLC442A), while the DNA methylation patterning of the remaining genes were identical between the groups." (PMID 34193262, 2021).
astrocytoma (1 paper, 2021). "BCL7A and BCL7B were identified as the two of the lowly expressed candidate genes associated with a small region of loss at 10q26.3 and 7q11.23 in astrocytoma, respectively." (PMID 34362400, 2021).
B-cell neoplasm (1 paper, 2025). A group of heterogeneous lymphoid tumors generally expressing one or more B-cell antigens or representing malignant transformations of B-lymphocytes. "Whole-exome sequencing revealed an elevated somatic copy number alteration burden and pathogenic variants in ARID1A, KMT2D, BCL7A, PTPN11, and NUP214, suggesting disruptions in chromatin remodeling, B-cell neoplasm pathogenesis, and oncogenic signaling driving the tumorigenesis." (PMID 41378284, 2025).